PIGV (phosphatidylinositol glycan anchor biosynthesis class V)
Description:
Alpha-1,6-mannosyltransferase that catalyzes the transfer of the second mannose, via an alpha-1,6 bond, from a dolichol-phosphate-mannose (Dol-P-Man) to a 2-acyl-6-(alpha-D-mannosyl-(1->4)-alpha-D-glucosaminyl)-1-(1-radyl,2-acyl-sn-glycero-3-phospho)-1D-myo-inositol (also termed H2) intermediate to generate a 2-acyl-6-[alpha-D-mannosyl- (1->6)-alpha-D-mannosyl-(1->4)-alpha-D-glucosaminyl]-1-(1-radyl,2-acyl-sn-glycero-3-phospho)-1D-myo-inositol (also termed H3) and participates in the seventh step of the glycosylphosphatidylinositol-anchor biosynthesis (Probable). May also transfer the second mannose on a 2-acyl-6-[2-phosphoethanolamine-alpha-D-mannosyl-(1->4)- alpha-D-glucosaminyl]-1-(1-radyl,2-acyl-sn-glycero-3-phospho)-1D-myo-inositol (also termed H5), but less effectively (Probable).
Synonyms: GPI-MT-II; PIG-V; FLJ20477; HPMRS1
Tractability: Antibody: UniProt predicts a signal peptide or a membrane-spanning region. PROTAC: ubiquitination databases record sites on it; its protein half-life has been measured.
Gene: Protein-coding gene on chromosome 1 (26,787,054 to 26,800,659, forward strand). Ensembl gene ENSG00000060642.
Subcellular location: Endoplasmic reticulum membrane
Subcellular location (Human Protein Atlas): Cytosol; Endoplasmic reticulum
Pathways (Reactome):
Metabolism of proteins: Synthesis of glycosylphosphatidylinositol (GPI)
Gene Ontology:
Molecular function: alpha-1,6-mannosyltransferase activity; dol-P-Man:Man(1)GlcN-acyl-PI alpha-1,6-mannosyltransferase activity; protein binding; GPI mannosyltransferase activity; mannosyltransferase activity
Biological process: GPI anchor biosynthetic process
Cellular component: endoplasmic reticulum; endoplasmic reticulum membrane; mannosyltransferase complex
Genetic constraint (gnomAD): Loss-of-function variants: 27 observed, 41.26 expected, observed/expected ratio (o/e) 0.65, 90% interval 0.48 to 0.9. The upper end of that interval is the gene's LOEUF score, 0.9, which puts it in group 3 of 6, group 1 being the genes least tolerant of losing a copy. Missense variants: 523 observed, 618.38 expected, observed/expected ratio (o/e) 0.85, 90% interval 0.79 to 0.91. Synonymous variants: 232 observed, 255.86 expected, observed/expected ratio (o/e) 0.91, 90% interval 0.81 to 1.01.
Gene-disease validity (ClinGen):
ClinGen rates the evidence that PIGV causes each of these diseases.
hyperphosphatasia with intellectual disability syndrome 1 (autosomal recessive): Moderate.
Homologues: Orthologues: chimpanzee PIGV (99% identical), macaque PIGV (97% identical), rabbit PIGV (85% identical), dog PIGV (84% identical), rat Pigv (80% identical), mouse Pigv (80% identical), pig PIGV (70% identical), zebrafish pigv (51% identical), tropical clawed frog pigv (47% identical), Drosophila melanogaster PIG-V (28% identical), Caenorhabditis elegans pigv-1 (24% identical).
Diseases named in the same sentence as PIGV in open-access papers:
PIGV is named in the same sentence as 29 diseases in open-access papers, as found by Europe PMC text mining. Sharing a sentence is not in itself a finding about the gene and the disease. The quoted sentences say what the papers report.
hyperphosphatasia (8 papers, 2015 to 2024). "Mutations in the PIGV gene lead to a disorder called hyperphosphatasia with impaired intellectual development syndrome 1 (HPMRS1), distinct from other CDGs in terms of hyperphosphatemia related to abnormal ALP activity and brachytelephalangy." (PMID 37372388, 2023). "Mutations in PIGV are thought to represent the major cause of ‘hyperphosphatasia with mental retardation syndrome'43 and so we were surprised that this gene did not come up in our analysis." (PMID 28327575, 2017). "Mutations in the human ortholog of C. elegans pigv-1, PIGV, have been associated in genetic studies with hyperphosphatasia-mental retardation syndrome (a.k.a Mabry syndrome)." (PMID 25807459, 2015). "PIGV and PIGO variants are associated with reduced GPI-AP surface levels and increased extracellular secretion into the extracellular space, resulting in hyperphosphatasia." (PMID 38790248, 2024). "This syndrome was named hyperphosphatasia with impaired intellectual development syndrome 1 (HPMRS-1, # 239300) and linked to mutations in the PIGV gene." (PMID 37372388, 2023). "Mutations in six different genes (PIGV, PIGY, PIGO, PGAP2, PIGW, and PGAP3) involved in GPI-anchor biosynthesis have been shown to cause hyperphosphatasia with mental retardation syndrome (HPMRS)." (PMID 29119105, 2017). "To date, mutations in six genes (PIGV, PIGY, PIGO, PGAP2, PIGW, and PGAP3) have been shown to cause hyperphosphatasia with mental retardation syndrome (HPMRS) in an autosomal recessive mode of inheritance (no autosomal dominant mutations have been reported thus far)." (PMID 29119105, 2017). "Further variant was PIGV:c.1022C>A (p.Ala341Glu) detected in one homozygous female (patient XIII) and two heterozygous females (patient XV and patient XVI), and classified in ClinVar as a cause of hyperphosphatasia with intellectual disability syndrome 1 (MIM #239300)." (PMID 37405542, 2023). "With the exception of hyperphosphatasia, which is known to be the result of loss of GPI-anchored complement inhibitors in blood cells, the proteins and cellular functions that are affected in humans with PIGV mutations are unknown." (PMID 25807459, 2015).
Mabry syndrome (7 papers, 2015 to 2025). "Hyperphosphatasia Mental Retardation syndrome (HPMRS, MIM 239300, MIM 214749, and MIM 614207), also known as Mabry syndrome, was found to be associated with PIGV (MIM 610274), PIGO (MIM 614730),PGAP2 (MIM 615187) and PGAP3 (MIM 611801) mutations." (PMID 25885527, 2015). "The current study introduces six new Polish patients diagnosed with Mabry syndrome who, despite possessing the most frequently found pathogenic mutation of the PIGV gene (c.1022C>A, p.(Ala341Glu)), presented with a phenotype very distinct from previously reported cases." (PMID 37372388, 2023). "Biallelic variants of the phosphatidylinositol glycan (PIG) biosynthesis, type V (PIGV) gene identified in Mabry syndrome became evidence of the first in a phenotypic series that is numbered HPMRS1-6 in the order of discovery." (PMID 38790248, 2024). "In addition to the PIGV variants identified in HPMRS1, pathogenic variants of at least three additional PIG genes expressed in the endoplasmic reticulum (ER) are also reported to result in Mabry syndrome." (PMID 38790248, 2024).
developmental delay (2 papers, 2018 to 2023). "In all cases, the same PIGV homozygotic mutation (c.1022C>A; p.Ala341Glu) was found, although the patients presented a diverse spectrum of neurological and developmental disorders, concerning in most cases the muscular tonus and general developmental delay." (PMID 37372388, 2023). "Furthermore, the cell surface levels of CD55 and CD59 were on average lower in cells that were derived from individuals with mutations in PGAP3 compared to individuals with mutations in PIGV, although this did not correspond to a higher prevalence of seizures or a more severe developmental delay." (PMID 29310717, 2018).
megacolon (2 papers, 2018 to 2023). "To date, megacolon has only been found to be associated with PIGV, PIGO, and PGAP2 mutations." (PMID 29310717, 2018).
congenital disorder of glycosylation (1 paper, 2023). Congenital disorder of glycosylation (CDG) is a fast growing group of inborn errors of metabolism characterized by defective activity of enzymes that participate in glycosylation (modification of proteins and other macromolecules by adding and processing of oligosaccharide side chains). "HPMRS-1 is currently also known as GPIBD2 or PIGV-congenital disorder of glycosylation (PIGV-CDG), due to its difference in terms of phenotype from the typical clinical image of GPIBDs which derives from its alterations of alkalic phosphatase (ALP) activity and consecutive hyperphosphatemia." (PMID 37372388, 2023).
deficiencies (1 paper, 2020). "Pyridoxine treatment was reported to be effective for seizures in some patients with inherited GPI deficiencies, such as PIGV or PIGO mutations." (PMID 32220244, 2020).
Fryns syndrome (1 paper, 2019). Fryns syndrome (FS) is a multiple congenital anomaly syndrome characterized by dysmorphic facial features, congenital diaphragmatic hernia, pulmonary hypoplasia, and distal limb hypoplasia, in addition to variable expression of additional malformations. "A homozygous missense variant in PIGW (c.[106 A>G];[106 A>G], p.(R36G) that segregated in both fetuses was prioritized because phenotypes caused by variants in PIGV and PIGN genes of the PIG family show a phenotypic overlap with Fryns syndrome or are described to be causal for the Fryns phenotype." (PMID 30679815, 2019).
cancer (4 papers, 2018 to 2023). A tumor composed of atypical neoplastic, often pleomorphic cells that invade other tissues. "Reduction of PIGV leads to disruption of the GPI anchor assembly, causing pro-PrP accumulation and enhancing cancer cell migration and invasion." (PMID 37390992, 2023). "We then investigated whether alteration of PIGV protein levels might affect cancer cell migration and invasiveness in vitro." (PMID 37390992, 2023).
tumor (2 papers, 2023). "A reduction in PIGV protein disrupts the GPI modification process, resulting in the conversion of GPI-anchored PrP into pro-PrP, rendering the tumor cells more aggressive." (PMID 37390992, 2023).
infection (1 paper, 2025). The state of being infected such as from the introduction of a foreign agent such as serum, vaccine, antigenic substance or organism. "Notably, knockout of PIGA, PIGV, or GPAA1 significantly increased the infection of other coronaviruses relative to controls, with the strongest effects observed for HCoV-229E (7-fold) and PEDV (20-fold)." (PMID 40901862, 2025). "Among the genes with the greatest positive effect on infection efficiency after knockout were multiple GPI biosynthesis genes: GPAA1, PIGA, PIGV, and DPM1 knockouts increased infection over 8-fold compared to control, while PIGO knockout increased infection approximately 4-fold." (PMID 40901862, 2025). "However, overexpression of PIGA or PIGV in unmodified HeLa cells did not alter infection by multiple coronaviruses relative to controls." (PMID 40901862, 2025).
PIGV also shares sentences with these, for which no sentence is quoted: genetic diseases (2 papers); Hirschsprung disease (2); Intellectual disability (2); anorectal malformation (1); autism (1); behavioural disorders (1); cervical cancer (1); Constipation (1); coronary heart disease (1); epilepsy (1); gastrointestinal disorders (1); glioma (1); hyperphosphatemia (1); ileus (1); intestinal disorder (1); neurological disorder (1); Obesity (1); paroxysmal nocturnal hemoglobinuria (1); sensory impairment (1).